NLRP3 (NLR family pyrin domain containing 3)
Diseases named in the same sentence as NLRP3 in open-access papers (continued):
Sharing a sentence is not in itself a finding about the gene and the disease.
HIV-1 infection (continued). "Recent studies have also linked polymorphisms in the inflammasome gene NLRP3 to an increased susceptibility to HIV-1 infection and HIV-1 has been implicated in priming the NLRP3 inflammasome in macrophages." (PMID 24886384, 2014). "NLRP3 sensing of HIV-1 has been suggested based on finding that IL-1β is upregulated during HIV-1 infection of human DCs." (PMID 23435233, 2013). "To show evidences of early inflammasome sensing of HIV-1 in huNSG mice upon HIV-1 infection, we quantified mRNA expression of genes involved in inflammasome activation (NLRP3, NLRP1, NLRC4, AIM2, IFI16, ASC, CASP1, IL1Β, and IL18) in hCD45+ cells from multiple tissues collected at necropsy." (PMID 36800238, 2023). "Additionally, in HIV-1 infection, the NLRP3 inflammasome pathway is activated and produces chronic inflammation." (PMID 37147420, 2023). "However, with the deepening of research, people found that NLRP3 inflammasome activation has a dual function in HIV-1 infection." (PMID 37465759, 2023). "HIV-1 infection provides the first of two signals for NLRP3 inflammasome activation." (PMID 32596261, 2020). "Gaps exist in our understanding to establish clear links between HIV-1 infection, NLRP3 inflammasome activation, and atherosclerotic disease with the approach of developing targeting therapies to reduce the inflammatory signaling that drives this important comorbidity." (PMID 32596261, 2020). "Whether HIV-1 infection leads to the formation of a RIPK1/RIPK3 complex that could promote NLRP3 inflammasome activation remains to be elucidated." (PMID 26297639, 2015). "As important mediators of inflammatory signaling and cell death, the NLRP3 inflammasome and purinergic receptors have been implicated in chronic inflammation in PWH, and P2X-selective antagonists have been shown to reduce inflammation associated with HIV-1 infection." (PMID 37027347, 2023). "We describe a key interaction between cannabinoids, the NLRP3 inflammasome, and HIV-1 viral infection, which supports further investigation of the critical role of cannabinoids in HIV-1 infection and inflammasome signaling." (PMID 37027347, 2023). "To date, activation of multiple inflammasomes including NLRP3, NLRC4 and IFI16 has been reported in HIV-1 infection, while numerous studies have also found that HIV-1-induced inflammatory responses and pyroptosis are also dependent on inflammasome." (PMID 37465759, 2023). "For example, abortive HIV-1 infection in quiescent lymphoid CD4 T cells leads to CD4 T cell pyroptosis independent of the NLRP3 inflammasome." (PMID 30634407, 2019). "In innate immune cells, such as monocytes/macrophages, dendritic cells and microglial cells, HIV-1 infection results in the activation of an inflammasome involving the PRR nucleotide-binding oligomerization domain (NOD), leucine-rich repeat (LRR)-containing proteins (NLR) family member 3 (NLRP3)." (PMID 36800238, 2023).
vasculitis (22 papers, 2017 to 2026). "We have previously reported that LCWE-induced KD vasculitis is associated with impaired autophagy/mitophagy and increased ROS production in inflamed vascular tissues, which promotes NLRP3 inflammasome activation and the development of cardiovascular lesions in LCWE-injected mice." (PMID 35167493, 2022). "Vasculitis associated with NLRP3-AID and comparison of NLRP3-AID with Behçet's syndrome." (PMID 34249981, 2021). "We also reviewed the English literature on vasculitis associated with NLRP3-AID." (PMID 34249981, 2021). "Spatial maps showed the activation of the NLRP3 inflammatory pathway and revealed the expression characteristics of key cell types in vasculitis, such as monocytes/macrophages/dendritic-like cells, 2 types of SMCs, and fibroblasts." (PMID 40062231, 2025). "It recruits inflammatory cells (e.g., Monocytes and neutrophils) via the CCRI pathway through its receptor CCR2, and activates the Dectin-2/NLRP3 inflammasome to induce IL-1β, driving vasculitis in KD models." (PMID 40455761, 2025). "Previous studies indicate that in LCWE-induced KD vasculitis, monocytes and macrophages are the main sources of IL-1B, while neutrophils and eosinophils also express transcripts (Il1b, Nlrp3, Casp1, and Pycard) and have the capacity to produce IL-1B." (PMID 37279077, 2023). "It found that the level of miR‐223 was increased during LCWE‐induced KD vasculitis, but miR‐223 appeared to reduce inflammation in vascular tissue by inhibiting NLRP3 activation and IL‐1β production." (PMID 37506144, 2023). "Our combined in vitro and in vivo data strongly suggest that IRE1 inhibition attenuates cardiovascular lesion formation in the murine KD vasculitis by diminishing NLRP3 activation." (PMID 35167493, 2022). "Collectively, our data reveal a previously unappreciated role of miR-223 in regulating innate immune responses and in limiting KD vasculitis and its cardiovascular lesions by constraining the NLRP3 inflammasome and the IL-1β pathway." (PMID 34026693, 2021). "LCWE-induced KD vasculitis is NLRP3 dependent, and it has been previously shown that miR-223 regulates NLRP3 activation and IL-1β production." (PMID 34026693, 2021). "Experimental data from murine models of KD vasculitis and transcriptomics data generated from whole blood of KD patients indicate the involvement of the NLRP3 inflammasome and interleukin-1 (IL-1) signaling in KD pathogenesis." (PMID 34026693, 2021). "Taken together, these results indicate that autophagy plays a key role in determining NLRP3 activation in the LCWE model of KD vasculitis." (PMID 34403365, 2021). "The LCWE-induced KD murine model of vasculitis is dependent on NLRP3 inflammasome activation, and as expected, IL-1β levels were increased in the serum of LCWE-injected mice compared with control PBS-injected mice." (PMID 34403365, 2021). "Studies in experimental murine models of KD vasculitis have confirmed those observations and further demonstrated the deleterious role of NLRP3 overactivation and enhanced IL-1β production during KD." (PMID 34026693, 2021). "The HMGB-1/RAGE signaling pathway in endothelial cells also induces cathepsin B activation, subsequently inducing canonical pyroptosis via NLRP3 inflammasomes in KD vasculitis." (PMID 34079539, 2021). "LA directly obstructed Syk phosphorylation and activity in a dose-dependent manner, inhibited the activity of p38 and JNK, and reduced the expression of NLRP3 in human umbilical vein endothelial cells and vascular tissue of rats with vasculitis." (PMID 30158835, 2018). "Given the pivotal role of NLRP3 inflammasome in KD pathogenesis and vasculitis development, VIM may contribute to the release of inflammatory mediators by modulating BAM and FAM." (PMID 40276515, 2025). "Activation of the innate immune system, particularly the endothelial Nlrp3 inflammasome induced by certain triggers, may lead to the development of coronary arteritis, which is a key feature in KD vasculitis." (PMID 38711494, 2024).
vasculitis (continued). "Impaired clearance of damaged mitochondria has been reported in the LCWE-induced murine model of KD vasculitis, shown by a decreased autophagic flux and blockade of autophagy by mTOR pathway activity, contributing to NLRP3 inflammasome activation and ROS accumulation." (PMID 38020895, 2023). "NLRP3-AID can hardly be seen with vasculitis, especially BS, though both belong to SAIDs." (PMID 34249981, 2021). "To further determine if miR-233 dampens LCWE-induced KD vasculitis in WT mice by decreasing NLRP3 inflammasome activation and subsequent IL-1β production, we next quantified the circulating levels of IL-1β in LCWE-injected WT and mir-223−/y mice 1 week after LCWE injection." (PMID 34026693, 2021). "Case reports revealed rare manifestations of vasculitis coexisting with NLRP3-AID." (PMID 34249981, 2021). "We also conducted a systemic review of NLRP3-AID with vasculitis." (PMID 34249981, 2021). "The enhanced cardiovascular lesions and KD vasculitis observed in LCWE-injected miR223−/y mice correlated with increased NLRP3 inflammasome activity and elevated IL-1β production, indicating that miR-223 limits cardiovascular lesion development by downmodulating NLRP3 inflammasome activity." (PMID 34026693, 2021). "However, the contribution of ER stress to NLRP3 activation and IL-1β secretion remains unknown in KD vasculitis." (PMID 35167493, 2022). "MicroRNA-223 (miR-223) is a negative regulator of NLRP3 activity and IL-1β production, and its expression has been reported to be upregulated during acute human KD; however, the specific role of miR-223 during KD vasculitis remains unknown." (PMID 34026693, 2021). "Another study shows that TMAO can partially activate the inflammatory corpuscles of NLRP3 by inhibiting the SIRT3-SOD2-mtROS signaling pathway of apolipoprotein E (ApoE)−/− mice, thus promoting vasculitis." (PMID 39834376, 2024). "Blocking the IL-1β pathway in mice, genetically or pharmacologically with either neutralizing antibodies or small-molecule inhibitors of NLRP3, prevents the development of LCWE-induced KD vasculitis." (PMID 35167493, 2022). "Moreover, Nucleotide-binding oligomerization domain-like receptor family, pyrin domain-containing 3 (NLRP3)-dependent endothelial cell pyroptosis via HMGB-1/RAGE/cathepsin B signaling may contribute to coronary artery endothelial cell (CAEC) damage in KD vasculitis." (PMID 34079539, 2021). "In fact, the flavonoid quercetin that inhibits NLRP3 inflammasome and ASC speck formation in mouse vasculitis and reduces pain in experimental gout arthritis." (PMID 30333752, 2018). "This study revealed the effects of LA on endothelial cell activation, NLRP3, IL-1β, TNF-α, IL-32, and CCL-2, VCAM-1, MCP-1, and the spleen tyrosine kinase (Syk)--p38/JNK signaling axis and its effect on vasculitis in rats." (PMID 30158835, 2018). "Vasculitis is one of the major manifestations of BS, but not NLRP3-AID." (PMID 34249981, 2021). "It is possible that IL-1β production by myeloid cells is already maximal after LCWE-injection, and autophagy might not be sufficient to regulate NLRP3 activation; thus, blocking autophagy specifically in myeloid cells did not further promote vasculitis severity." (PMID 34403365, 2021). "However, LCWE-induced KD vasculitis was similar between LysMCreAtg16l1Δ/Δ and Atg16l1fl/fl littermate controls, indicating that blocking autophagy specifically in myeloid cells did not affect NLRP3 activation in this model." (PMID 34403365, 2021). "We found that autophagy and mitophagy were impaired during LCWE-induced murine KD vasculitis and that genetic, nonpharmacologic and pharmacological modulation of autophagic flux decreased the severity of LCWE-induced cardiovascular inflammation by blocking NLRP3 activation and IL-1β secretion." (PMID 34403365, 2021).
Arrhythmia (21 papers, 2016 to 2025). Any cardiac rhythm other than the normal sinus rhythm. "The MCC950-mediated reduction in VA incidence in the RVOTs of the experimental group suggests that inhibiting NLRP3 with MCC950 reduces the risk of arrhythmia by suppressing arrhythmogenesis in the RVOT." (PMID 38650023, 2024). "SCFA treatment can inhibit NF-κB/NLRP3 signaling, which may prevent inflammation-associated heart arrhythmia." (PMID 34201938, 2021). "In arrhythmias, the activation of NLRP3 inflammatory vesicles induces the upregulation of ultrarapid delayed rectifier K+ channels and shortening, which leads to myocardial potentiostatic inappetence and action potential duration." (PMID 39022620, 2024). "EA regulated the activation of NLRP3, polarization of macrophages, declined arrhythmia scores, improving cardiac function." (PMID 32738910, 2020). "We further show that DM-induced arrhythmias can be successfully treated by inhibiting the IL-1β axis with either IL-1 receptor antagonist or by inhibiting the NLRP3 inflammasome." (PMID 27882934, 2016). "Our study also reveals a novel treatment option of DM-related arrhythmias by using either an IL-1β receptor antagonist (anakinra) or a NLRP3 inhibitor (MCC-950)." (PMID 27882934, 2016). "This suggests that the activation of NLRP3 inflammatory vesicles may be a key driver for the development of arrhythmias." (PMID 39022620, 2024). "Activation of the NLRP3 inflammasome plays a vital role in the pathogenesis of cardiac arrhythmia." (PMID 38650023, 2024). "Studies from other group also revealed DM-induced arrhythmias could be successfully treated by inhibiting the IL-1β axis with either IL-1 receptor antagonist or by inhibiting the NLRP3 inflammasome." (PMID 33681353, 2021). "Importantly, Nlrp3−/− and Casp1−/− diabetic mice had lower arrhythmia vulnerability and severity in response to Caff/Dobu challenge when compared with diabetic WT mice." (PMID 27882934, 2016). "Interestingly, TET2-deficient mouse models demonstrated that inflammation via the NLRP3 inflammasome and calcium handling abnormalities in atrial cells contributed to AF susceptibility, findings that were further proved by the decreased arrhythmia incidence after NLRP3 inhibition." (PMID 40804878, 2025). "As we have shown that cardiac macrophages produce IL-1β and upregulate NLRP3 expression in response to TLR2 stimulation promoted by DM, we tested whether the NLRP3 inflammasome is involved in the DM-induced cardiac electrical disturbances and susceptibility to arrhythmias." (PMID 27882934, 2016). "Also, arrhythmias may result from inflammasome activation, such as in atrial fibrillation driven by NOD-, LRR-, and pyrin domain-containing protein 3 (NLRP3) inflammasome activation in post–open-heart surgery and in obesity." (PMID 36341442, 2022). "Mutant mice treated with the NLRP3-inhibitor MCC950, show normal EF and fractional shortening, develop no arrhythmias and show no cardiac fibrosis unlike vehicle-treated littermates." (PMID 39392548, 2025).
Cirrhosis (21 papers, 2018 to 2026). A chronic disorder of the liver in which liver tissue becomes scarred and is partially replaced by regenerative nodules and fibrotic tissue resulting in loss of liver function. "Previous studies have found higher NLRP3 and caspase-1 expression levels in liver of patients with cirrhosis." (PMID 37370025, 2023). "The NLRP3 inflammasome is significantly activated in a CCL4-induced mouse model of cirrhosis, which aggravates hepatocyte death and cirrhosis through the NLRP3/caspase-1/GSDMD classical pyroptosis pathway." (PMID 37370025, 2023). "The hepatotropic viruses evade the NLRP3 inflammasome in order to sustain the chronicity of infection leading to cirrhosis while in the established tumors the activation of NLRP3 promotes several pro-tumorigenic effects." (PMID 35804922, 2022). "In fact, how NLRP3 inflammasome participate the pathological process of viral hepatitis, cirrhosis and HCC remains mainly unclear, which may be due to the difficulties to constructing proper research models." (PMID 38817443, 2024). "Meanwhile, numerous chemical agents and botanic drugs have been intensively tested as inhibitors for NLRP3 inflammasome and its constituents as effective modalities in prevention of HCC development from precedent hepatitis, fibrosis, and cirrhosis." (PMID 36330474, 2022). "STING and NLRP3 signaling pathways are activated in cirrhosis, and both knockdown of STING and STING inhibitor C-176 significantly inhibited NLRP3 expression and hepatocyte pyroptosis, suggesting that STING can induce hepatocyte pyroptosis through activation of the NLRP3 inflammasome." (PMID 38195584, 2024). "The comparison between the AUC of the ROC curves showed that serum NLRP3 (AUC = 0.971) was superior to APRI (AUC = 0.754, z = 2.1004, P = 0.036) but was comparable to FIB-4 (AUC = 0.806, z = 1.7829, P = 0.075) in the diagnosis of advanced fibrosis/cirrhosis." (PMID 36376416, 2022). "In addition, NLRP3 in HCC tissues has low expression in comparison with noncancerous tissues (such as cirrhosis), but it is significantly higher than normal tissues." (PMID 34502191, 2021).
endometritis (21 papers, 2018 to 2025). An acute or chronic, usually bacterial infectious process affecting the endometrium. "In our previous research, we demonstrated that the NLRP3 inflammasome was activated in mice with endometritis induced by LPS, and NLRP3 deficiency significantly reduced uterine damage." (PMID 40723465, 2025). "Here we show NLRP3 inflammasome activation is essential for driving a macrophage-associated endometritis resulting in infertility by using a female mouse genital tract chlamydial infection model." (PMID 34526512, 2021). "Paradoxically, a consequence of CT135 mediated neutrophil killing results in a submucosal macrophage-associated endometritis driven by ATP/P2X7R induced NLRP3 inflammasome activation." (PMID 34526512, 2021). "Moreover, our previous study provides genetic evidence that NLRP3 ablation suppresses NLRP3 inflammasome activation in LPS-induced murine endometritis, establishing a causal role of NLRP3 in endometritis pathogenesis through reverse validation." (PMID 40723465, 2025). "Excessive NLRP3 inflammasome activation causes tissue damage and immune dysfunction, leading to the occurrence and development of several inflammatory diseases, such as endometritis." (PMID 37570258, 2023). "All results demonstrated that NLRP3 inflammasome is activated and Ang is upregulated in porcine endometritis." (PMID 40723465, 2025). "The results observed in porcine and mouse models in this study reveal a key regulatory role of Ang in NLRP3 inflammasome activation during endometritis." (PMID 40723465, 2025). "The results demonstrate that NLRP3 inflammasome activation and Ang upregulation occur in porcine endometritis." (PMID 40723465, 2025). "Intraperitoneal melatonin injection, which promotes autophagy to inhibit mtROS-dependent NLRP3 inflammasome activation, inhibits LPS-induced endometritis and exhibits anti-inflammatory effects." (PMID 40431224, 2025). "Taken together, these results provide evidence that Ang inhibits NLRP3 inflammasome activation and holds promise as a potential target for the prevention and treatment of endometritis." (PMID 40723465, 2025). "Western blot results showed that the NLRP3 inflammasome was activated in cases of porcine endometritis, as evidenced by an increased protein level of NLRP3, pro-Caspase1, cleaved-Caspase1, and ASC." (PMID 40723465, 2025). "The results demonstrated NLRP3 inflammasome activation in endometritis, evidenced by elevated protein levels of NLRP3, ASC, pro-Caspase-1, and cleaved Caspase-1, concurrent with Ang upregulation." (PMID 40723465, 2025). "Previous studies have shown that miR-495 can suppress NLRP3 inflammasome activation, protecting against pyroptosis and bovine endometritis." (PMID 40723465, 2025). "Taken together, these results clearly demonstrate that the NLRP3 inflammasome is activated in the pathogenesis of endometritis, and that the uterine pathological response is enhanced in Ang−/− mice." (PMID 40723465, 2025). "Taken together, these studies highlight the potential for developing new therapeutic approaches to inhibit NLRP3 activity and enhance the resolution of endometritis." (PMID 40723465, 2025). "This study aimed to investigate NLRP3 inflammasome activation and Ang expression dynamics during endometritis, and to elucidate the functional role of Ang in this disease via the Ang deficiency mouse model." (PMID 40723465, 2025). "Consistent with porcine results, the NLRP3 inflammasome was activated in the uterine tissue of mice with endometritis, as evidenced by increased levels of the proteins NLRP3, ASC, pro-Caspase1, and cleaved-Caspase1." (PMID 40723465, 2025). "In this study, we observed severe damage and significant neutrophil infiltration in the uteri of pigs and mice with endometritis, where NLRP3 inflammasome activation was also present." (PMID 40723465, 2025).